RNU6-835P (RNA, U6 small nuclear 835, pseudogene)
Gene: Small nuclear RNA gene on chromosome 14 (87,996,345 to 87,996,448, reverse strand). Ensembl gene ENSG00000252783.
Homologues: Orthologues: chimpanzee U6 (99% identical), dog U6 (79% identical). Paralogues in human: RNU6-1083P (84% identical), RNU6-1091P (83% identical), RNU6-1310P (83% identical), RNU6-43P (83% identical), RNU6-1036P (82% identical), RNU6-398P (82% identical), RNU6-726P (82% identical), RNU6-854P (81% identical), RNU6-1056P (80% identical), RNU6-1094P (80% identical), RNU6-11P (80% identical), RNU6-1311P (80% identical), and 1288 more.